LPL (lipoprotein lipase)
Diseases named in the same sentence as LPL in open-access papers (continued):
Sharing a sentence is not in itself a finding about the gene and the disease.
Obesity (continued). "Actually, presence of LPL P+/-, P+/+ genotypes that we investigated in our study might, as a predictive risk factor related to obesity-related metabolic disorder, indicate the need for individualized diet adjustments." (PMID 19804633, 2009). "Then, variation of LPL activity among fat depots as well as ratio of adipose tissue to skeletal muscle LPL activity, have been proposed to be linked to the development of regional obesity under certain genetic predisposition." (PMID 15588304, 2004). "The association between LPL activity and obesity might be tissue specific." (PMID 35456470, 2022). "Additionally, the risk of extreme obesity (BMI ≥ 40 kg/m2) was about fourfold increased for minor allele carriers for both SNPs, suggesting that c.56C > G and LPL m107 could interact to modulate obesity." (PMID 30053818, 2018). "These cells mostly arise in adipose tissue during obesity and are characterized by the expression of genes associated with lipid metabolism, including TREM2, CD9 and lipoprotein lipase (LPL)." (PMID 41409275, 2025). "Several single-nucleotide polymorphisms (SNPs) across the lipoprotein lipase (LPL) gene have been found to be associated with dyslipidemia and obesity." (PMID 40806414, 2025). "Wistar rats were chosen in this study for their higher susceptibility to HFD-induced obesity than Sprague-Dawley rats, attributed to elevated cluster of differentiation 36 (CD36) and lipoprotein lipase expression." (PMID 40563378, 2025). "In the early stages of obesity, ligand–receptor interactions involving LPL, LRP1, and ApoE in ATM contribute to lipid signaling, which regulates inflammation and shapes the metabolic microenvironment of adipose tissue." (PMID 40244284, 2025). "Reduction or loss of LPL activity in endothelial cells led to impairment of tissue function in the body, it could reduce the uptake of lipoprotein-derived fatty acids, which can lead to metabolic diseases (e.g., hypercholesterolemia, diabetes, obesity, and most importantly, CHD)." (PMID 40177096, 2025). "We found that obesity was associated with increased expression of the PAR2 gene, F2RL1, and decreased expression of the LPL gene." (PMID 38973609, 2024). "We found that the expression of PAR2 was significantly increased in WAT isolated from patients with obesity and was inversely correlated with the LPL gene." (PMID 38973609, 2024). "LPL catalyzes the hydrolysis of triglycerides, playing a key role in the efficient uptake and storage of fatty acid in cells; therefore, regulation of LPL function in adipocytes is intently connected to obesity." (PMID 38393062, 2024). "The LPL and APIPOQ genes of this cluster are associated with obesity induced by the consumption of high-fat foods and show a strong association with the PPARG gene, which forms the second cluster." (PMID 36982283, 2023). "They prevent obesity by inhibiting the action of lipoprotein lipase, which determines the accumulation of triglycerides in adipocytes." (PMID 38136211, 2023). "The current study examined the association of the LPL S447X polymorphism with T2DM and obesity in the Kurdish population of Iraq." (PMID 36605456, 2023). "Under high-fat high-carbohydrate conditions, Lpl deficiency enhances weight gain and glucose intolerance, reduces phagocytic activity and mitochondrial dysmorphia, indicating microglial LPL maintains hypothalamic integrity in obesity." (PMID 36994095, 2023). "LPL hydrolyzes triglyceride (TG) into fatty acid and glycerol and hepatic lipase deficiency exhibited glucose intolerance and hepatic steatosis, whereas increasing LPL rescued glucose and insulin tolerance in high fat diet-induced obesity." (PMID 37033452, 2023). "Microbial suppression of the FIAF, a peptide potent inhibitor of LPL, promotes obesity, as well as the major synthesis of angiopoietin-like factor IV." (PMID 38136211, 2023).
Obesity (continued). "The present study aimed to investigate the association between lipoprotein lipase (LPL) S447X polymorphism and type 2 diabetes mellitus (T2DM), obesity, lipid profile, and oxidative stress parameters in a population from the Kurdistan region of Iraq." (PMID 36605456, 2023). "SNP rs328 of LPL gene significantly affects the blood levels of hormones, adipokines, and myokines in children and adolescents with obesity in gender-dependent manner." (PMID 37901192, 2023). "The effects of obesity on LPL and other fatty acid transporters are inconsistent based on the model studied, the diet, and the time of gestation." (PMID 38133242, 2023). "Our data showed significantly lower expression of LPL in participants with obesity especially among those with diabetes." (PMID 35933445, 2022). "ABCG1 has been reported to promote LPL-dependent triglyceride storage in adipocytes and to modulate ATM cholesterol content in obesity and weight loss regimes, leading to an alteration in M1 to M2 ratio." (PMID 36557031, 2022). "Loss of Lipc protects against, whereas liver-specific overexpression of LPL promotes diet-induced obesity and hepatic steatosis." (PMID 35614477, 2022). "Beyond the well-established implication of LPL activity in obesity and type 2 diabetes, our results suggest that LPL also plays an important role in the detoxification of bacterial toxins and the attenuation of inflammation." (PMID 36362012, 2022). "Dysfunction of LPL system can lead to the manifestation of atherosclerosis, chylomicronemia, dyslipidemia, obesity." (PMID 35241081, 2022). "Next, we compared lower TG levels via APOA5 and LPL variation with over 100 lipoprotein measurements in a combined sample from the Netherlands Epidemiology of Obesity study (N = 4,838) and the Oxford Biobank (N = 6,999)." (PMID 35278410, 2022). "Accumulating evidence suggests that the decrease of LPL activity in epididymal adipose and the improvement in skeletal muscle has the beneficial effect of preventing diet-induced obesity." (PMID 35885328, 2022). "Orlistat is used as an anti-obesity drug and acts by binding to the active sites of LPL, thus inhibiting the hydrolysis of triglycerides to free FAs." (PMID 36500977, 2022). "Some nucleotide variations (SNVs) in obesity-related genes, such as LEP 2548G/A and 668A/G in the LPR and LPL, have been associated with preeclampsia." (PMID 35252239, 2022). "Inhibition of LPL with small molecular compounds has been widely used in the clinic to treat obesity‐related syndromes, including diabetes and cardiovascular diseases." (PMID 34632719, 2021). "Our key findings were the robust POE of variants at the LPL and DOCK7/ANGPTL3 loci on obesity measures in both family cohorts, and the same variants also showed POE on lipid traits in the Botnia family study." (PMID 35052431, 2021). "Variants at LPL and DOCK7/ANGPTL3 showed POE on obesity-related traits in Botnia and HTB, and POE effects on obesity were seen to a higher degree in daughters." (PMID 35052431, 2021). "We found that LPL, APOA5, and CETP were associated with the metabolically unhealthy phenotypes in individuals with normal weight or obesity." (PMID 33500527, 2021). "In the case of lipid metabolism, it is known that in obesity, the impaired ability to up-regulate LPL by insulin exacerbates hepatic postprandial lipid load, thus causing hepatic steatosis." (PMID 33859314, 2021). "Patients with obesity or metabolic syndrome tend to have low HDL-C because of lower lipoprotein lipase activity and TG enrichment." (PMID 34644321, 2021). "In this study, down-regulation of gene expression of PPARγ, C/EBPα, SREBP-1c, aP2, FAS, LPL, and leptin in 3T3-L1 adipocytes by 18KHT01 suggested the potential effect of 18KHT01 on preventing adipogenesis, so prevent obesity." (PMID 34975503, 2021).
Obesity (continued). "The fetal liver exhibited steatosis, enhanced oxidative stress, and increased expression of acetyl-CoA carboxylase 1 and lipoprotein lipase with changes in maternal HF diet and obesity." (PMID 34977107, 2021). "In our study, we observed a higher gene expression of LPL and ACC isoform 1 in fetal liver associated with maternal HF diet/obesity." (PMID 34977107, 2021). "Here, we describe a simple, rapid fluorescence-based method to determine the lipolytic activities of different lipases, particularly ATGL, HSL, LpL, and PTL because of their relevance to hyperlipidemia, obesity, and associated metabolic diseases." (PMID 34508728, 2021). "This study was designed to explore VAT ANGPTL4 and LPL expression levels in human obesity in relation to adipose tissue inflammation, impairment in glucose metabolism, and clinical outcomes." (PMID 33003532, 2020). "We reasoned that, since mice with a neuron-specific LPL depletion show hyperphagia, inactivity, and obesity, autonomic regulation of the peripheral metabolic organs such as the liver was likely." (PMID 32998280, 2020). "After capsaicin removal by chloroform defatting, the freeze-dried powder of Cca was administered to 3T3-L1 cells, and the anti-obesity effects were observed by assessing the LPL mRNA level via the RT-PCR protocol." (PMID 32707790, 2020). "Here, we show that, despite obesity, mice with reduced neuronal LPL (NEXCreLPLflox (LPL KD)) show improved glucose tolerance and reduced hepatic lipid accumulation with aging compared to wilt type (WT) controls (LPLflox)." (PMID 32998280, 2020). "Diet encouraged over-expression of human LPL hinders the diet-induced obesity in the skeletal muscles of transgenic mice." (PMID 32847584, 2020). "We identified that NDGA, as an LPL inhibitor, effectively worsened obesity and metabolic complications including dyslipidemia, HDL particle size alteration, and adipose inflammation." (PMID 31234537, 2019). "With regards to microglial metabolism in obesity, it was recently reported that impairing lipid uptake, through the silencing of lipoprotein lipase (LPL), specifically in microglia, exacerbates weight gain and glucose intolerance in mice fed an HFHC diet." (PMID 31068773, 2019). "We have previously shown that a decrease in the expression of LPL in hippocampus or hypothalamus led to the development of obesity and dysregulation of energy homeostasis." (PMID 29593657, 2018). "LPL is thus considered a gatekeeper enzyme to play an important role in the initiation and development of obesity." (PMID 29075849, 2018). "Studies in both fish and mammals have shown that LPL is closely related to lipid metabolism in the body and obesity." (PMID 30344495, 2018). "Interactions between BMI and LPL polymorphisms or between birth weight and LPL polymorphisms may explain how subjects with a certain genotype fail to maintain homeostasis and ideal levels of plasma lipids only after the environmental challenge of increasing obesity." (PMID 26786614, 2016). "To further determine the potential role of liver LPL in obesity, we fed male LplΔhep and control mice with a HFD for 16 weeks." (PMID 27234787, 2016). "The comparison between KK and KK-Ay mice indicates that suppression of the hepatic mTORC1/S6K pathway in KK-Ay mice restored obesity-related adipose LPL downregulation and serum TG elevation to degrees similar to those in lean KK mice." (PMID 26268630, 2015). "The present results indicate that, in the state of obesity, the hepatic mTORC1/S6K pathway is physiologically activated, leading to downregulation of LPL in adipose tissue via a neuronal relay." (PMID 26268630, 2015). "Under conditions of high triglyceride availability (as occurs in obesity), the liver secretes greater amounts of large precursor lipoproteins which are delipidated by lipoprotein lipase and hepatic lipase directly to sdLDL." (PMID 25925050, 2015).
Obesity (continued). "Lipolysis of TG-rich lipoproteins is impaired in obesity by reduced mRNA expression levels of LPL in adipose tissue, reductions in LPL activity in skeletal muscle and competition for lipolysis between VLDL and chylomicrons." (PMID 23584084, 2013). "BMI values and prevalence of obesity decreased with increasing LPL quartiles, but the trend was borderline significant." (PMID 23320821, 2013). "Reduced expressions of fatty acid synthetase, PPARγ, and LPL in adipose tissue suppress the onset of obesity." (PMID 23365609, 2013). "Given the importance of LPL for lipid metabolism, its activity would be expected to be intimately involved in obesity effects and development of the metabolic syndrome." (PMID 22028972, 2012). "LPL has been reported to play key roles in many human diseases, such as atherosclerosis, obesity, type 2 diabetes, chylomicronaemia, Alzheimer's disease, and cachexia." (PMID 22028972, 2012). "Lipoprotein lipase (LPL) has also been targeted in obesity as it has been found out that there is an increase in LPL level in obese subjects." (PMID 22666121, 2012). "A large number of studies in rodents and humans have revealed that obesity results in increased LPL activity in adipose tissue." (PMID 22028972, 2012). "Activity of lipoprotein lipase (LPL) is an important determinant in the development of obesity in mouse models." (PMID 22471940, 2012). "Dysregulation of LPL has been reported to contribute to many human diseases, such as atherosclerosis, chylomicronaemia, obesity, and type 2 diabetes." (PMID 22028972, 2012). "Reduced expressions of fatty acid synthetase, PPARγ and LPL in the liver suppress the onset of obesity and fatty liver." (PMID 21799697, 2011). "Our results indicate that the greater the degree of obesity the lower the gene expression of genes related with lipid processing in adipose tissue (LPL, FABP4, ASP and LRP1), both visceral and subcutaneous, though more obviously in the VAT." (PMID 21966368, 2011). "The findings also demonstrate the potential beneficial effects of calcium channel blockers on cSVD imaging markers and cholesteryl ester transfer protein inhibitors, lipoprotein lipase enhancement and gastric inhibitory polypeptide receptor obesity-targeted drugs on LS." (PMID 39661645, 2025). "Similarly, in high-fat diet (HFD) induced obesity mouse models, the expression of Lipoprotein Lipase (LPL) and APOE in adipose tissue macrophages is upregulated through a TREM2-dependent mechanism." (PMID 40636122, 2025). "Decreased expression of MTFP1 was linked to increased expression of PPARG (Peroxisome Proliferator-Activated Receptor Gamma) and LPL (Lipoprotein Lipase), two known obesity-related genes important for adipogenesis, lipid metabolism, and ultimately energy homeostasis." (PMID 40216759, 2025). "In obesity, under conditions of excess energy, mTOR enhances the transcriptional activity of PPARγ and increases the synthesis of proteins involved in lipid metabolism, such as lipoprotein lipase (LPL) and glycerol kinase (GyK)." (PMID 41287647, 2025). "Additionally, other reports suggested that cyanidin and cyanidin-3-O-β-D-glucoside exhibited their anti-obesity potential by inhibiting pancreatic lipase enzyme or stimulating lipoprotein lipase (LPL) activity." (PMID 40368975, 2025). "The levels of these lipoproteins are influenced by a variety of lipid metabolism and transport mechanisms, which result in defective LPL structures/functions, and may often manifest into dyslipidemia and other metabolic disorders including obesity." (PMID 40806414, 2025). "As discussed by the authors, an insufficient lipoprotein lipase activity, e.g. in obesity or CKD, might result in elevated LDL-TG levels and the increased atherosclerotic risk." (PMID 41239356, 2025). "In addition, the higher activity of lipoprotein lipase (LPL) in subcutaneous adipocytes of the lower body in women suggests greater TG clearance compared to visceral adipocytes in men with obesity." (PMID 40299427, 2025).
Obesity (continued). "Gut microbiota may regulate obesity by modulating the expression of LPL inhibitor FIAF expression, which influences energy extraction and distribution." (PMID 39200098, 2024). "The literature on gut microbiota and obesity reported that RSV could significantly increase the fasting‐induced expression of circulating lipoprotein lipase inhibitor (lipoprotein lipase inhibitor)." (PMID 38151750, 2024). "By screening adipogenesis genes, we also found that MIF deletion increased LPL gene expression in adipose tissue which may also contribute to the development of adipocyte hypertrophy and obesity." (PMID 37935315, 2024). "Obesity combined with pregnancy can trigger an increase in maternal circulating lipids with advancing gestation, resulting in excess lipid transfer to the developing fetus via placental LPL activity." (PMID 39458497, 2024). "Consequently, the consumption of excessive dietary fats or nutrients stimulates adipocyte hypertrophy and obesity after excessive LPL mediated TAG hydrolysis and low in relative quantity of dietary fat storage." (PMID 38755663, 2024). "Furthermore, impaired triglyceride clearance across adipose tissue is observed in obesity, insulin resistance, and type 2 diabetes (T2D) due to reduced insulin-mediated stimulation of LPL activity." (PMID 38755663, 2024). "Indeed, adipose LPL is impaired in obesity, and underexpression of adipose LPL reduces fatty acid entry into WAT." (PMID 38973609, 2024). "We report the influence of obesity on lipid profile in diabetic and nondiabetic individuals and the effect of LPL SX genotype on decreased risk of T2DM and reduced levels of FBS and TOS." (PMID 36605456, 2023). "Furthermore, an increased expression of LPL in microglia appears to have a protective effect against AD and obesity." (PMID 37342358, 2023). "Additionally, reduced LPL activity in skeletal muscles and decreased expression of LPL in adipose tissue will further slowdown the lipolysis of triglycerides from lipoproteins in individuals with obesity." (PMID 37396133, 2023). "Since the exact mechanism of lipid metabolism dysfunction in diabetes is not fully understood and also the effect of ethnicity on the identification of genes study should not be ignored, the current study was performed to examine the possible association of LPL S447X variants with T2DM and obesity." (PMID 36605456, 2023). "The investigations of circulating apolipoproteins and ANGPTLs related to LPL in diabetes and obesity are important, as the inhibitors against APOC3 and ANGPTL3 using antibodies, antisense oligonucleotides and silencing ribonucleic acids are currently under development." (PMID 37448184, 2023). "In addition, lipid accumulation and significant upregulation of LPL and CD36 expression were discerned in N + tumor tissue samples and obesity cases, further strengthening the association of lipid metabolism with LNM." (PMID 36397145, 2022). "This suggests that SNPs that alter LPL activity in muscle and adipose tissue could affect obesity related traits." (PMID 35807893, 2022). "Consequently, compounds that can regulate activity of LPL in muscles tissue and adipose tissue are supposed to function as anti-obesity agents." (PMID 35885328, 2022). "The results also suggested that RSE prevented obesity through preferentially directing triglycerides to energy production by the muscle instead of to energy storage by the adipose tissue via the regulation of LPL activity in different tissues." (PMID 35885328, 2022). "Overall, these findings suggested that RSE from the red skin of lotus seeds could serve as a great candidate for a value-added, functional ingredient due to its anti-obesity effects via the regulation of LPL activity." (PMID 35885328, 2022).